IDH1 (isocitrate dehydrogenase (NADP(+)) 1)
Diseases named in the same sentence as IDH1 in open-access papers (continued):
Sharing a sentence is not in itself a finding about the gene and the disease.
glioma (continued). "It is suspected that pGBM with IDH1 mutation may evolve from relative low grade glioma although without surgery history." (PMID 22291938, 2012). "Furthermore, the incidence of IDH1/2 mutation in deeply located gliomas (35.7%) showed a trend to be lower than that of non-deeply located gliomas (59.8%) (P = 0.075)." (PMID 22427879, 2012). "In addition, glioma cell culture collections can be analysed, and none of the 15 commercially available cell lines presents IDH1 mutation." (PMID 21326241, 2011). "However, it is unclear whether binding to IDH1-WT or IDH2-WT is shared by all of the glioma-derived IDH mutants, or whether IDH mutants actually bind a significant portion of IDH1-WT or IDH2-WT molecules to exert this dominant negative function in cells." (PMID 21326614, 2011). "In gliomas, both MK and PTN are consistently overexpressed, with expression increasing alongside tumor grade in IDH1 wild-type tumors, correlating with poor patient survival." (PMID 41955968, 2026). "Inhibitors of IDH1/2 act at the interface of epigenetic and metabolic vulnerabilities and have been FDA‐approved for the treatment of IDH‐mutant glioma, cholangiocarcinoma, and myeloid malignancies." (PMID 40181550, 2026). "In an analysis of chromosomal alterations across glioma subtypes (81 GBM, 48 IDH1/2-mutant astrocytomas, and 25 oligodendrogliomas), distinct genomic instability patterns were identified." (PMID 41377022, 2025). "Blockade experiments revealed that combining CD47 inhibitor RRx‐001 with IDH1‐R132H inhibitor ivosidenib synergistically enhances TAM phagocytosis and glioma clearance, offering a novel combinatorial strategy." (PMID 40654157, 2025). "The IDH1 and IDH2 are frequently observed in various cancers, including gliomas and acute myeloid leukemia (AML)." (PMID 40183077, 2025). "Interestingly, this aligns with clinical observations that IDH1-wt tumors often exhibit reduced sensitivity to temozolomide, as previously reported in studies showing a higher rate of temozolomide response in IDH1-mutant low-grade gliomas compared to their IDH1-wt counterparts." (PMID 40362411, 2025). "In glioma cells, SIRT7 knockdown leads to decreased IDH1 protein and mRNA levels, suggesting a positive regulatory role of SIRT7 on IDH1 expression." (PMID 40710366, 2025). "After observing significant effects of RNaseH2 inhibitor candidates on glioma cell survival in combination with TMZ, we extended our investigation to GBO-PDC (IDH1 WT)." (PMID 41285884, 2025). "The strong frontal lobe preference of IDH1/2-mutant gliomas may be associated with their epigenetic features in OLIG2-positive precursor cells existing in this region, potentially driving selective expansion of IDH1/2-mutant clones through aberrant metabolic reprogramming." (PMID 41377022, 2025). "Given the elevated H2O2 and reduced GSH levels in IDH1‐MUT GL261 tumor, H2O2/GSH mapping serves as a parameter to differentiate glioma genotypes." (PMID 40171868, 2025). "Recently, the combined evaluation of DCE-MRI and DKI was proposed to facilitate the prediction of high-grade (HGG) vs. low-grade gliomas (LGG), IDH1/2 wildtype vs. IDH1/2 mutant gliomas, and high-grade oligodendroglial vs. high-grade astrocytic gliomas." (PMID 40075780, 2025). "Vorasidenib, a brain-penetrant dual inhibitor of mutant isocitrate dehydrogenase 1 and 2 (IDH1/2), represents a significant advancement in the management of IDH-mutant gliomas." (PMID 40657255, 2025). "In general, BrM markers such as AE1/AE3, CK7, and EMA were consistently distributed across M0−M6, whereas M7−M10 was positively correlated with glioma characteristics, including WHO grade and IDH1 status." (PMID 39716938, 2025).
glioma (continued). "The patients were categorized into groups based on glioma grade to further examine the link between the ultrasonography characteristics of LGG and HGG and IDH1 expression." (PMID 40944023, 2025). "FDA-approved drugs such as ivosidenib and enasidenib, which target IDH1 and IDH2 respectively, have shown clinical efficacy in treating IDH-mutant AML, glioma, and cholangiocarcinoma, both as monotherapies and in combination therapies." (PMID 40641934, 2025). "In line with studies performed in glioma cells, HCT116 colon cancer cells expressing the IDH1-R132H mutant consume significantly greater quantities of NADPH compared with wildtype cells." (PMID 39596840, 2024). "Subsequent advancements led to vorasidenib, a dual IDH1 and IDH2 inhibitor, which demonstrated favorable safety in a phase I glioma cohort." (PMID 39529768, 2024). "Mutated versions of isocitrate dehydrogenase enzymes, cytoplasmic IDH1 and mitochondrial IDH2, are frequently found in gliomas." (PMID 39011394, 2024). "Radiomic features were also used to determine the genetic profiles of ATRX, IDH1/2, MGMT and 1p19q in gliomas." (PMID 38486342, 2024). "Although this is the largest series of IDH1/2 wt grade II and III gliomas, our study harbors drawbacks." (PMID 38326661, 2024). "We treated IDH1 WT cell line HK157 and 2 IDH1 MT glioma cell lines, HK252 and BT142, with VPA for four days and examined phosphorylation of ribosomal protein S6 (PS6) and FASN protein expression." (PMID 39149696, 2024). "Mutations in the metabolic enzymes isocitrate dehydrogenase 1 and 2 (IDH1 and IDH2) occur in more than 70% of low-grade glioma and approximately 12% of high-grade glioma." (PMID 37982850, 2024). "To evaluate the potential of [18F]AG-120 to detect IDH1R312H-positive brain tumors in vivo, we implanted the transfected U251 cells stereotactically in nude rats to generate a suitable model of IDH1 and IDH1R132H-positive glioma (n = 2 for each cell type)." (PMID 37982850, 2024). "The isoenzyme IDH1, a member of the IDH family, exhibits significant upregulation and enhances cell migration in patients with primary gliomas." (PMID 39584783, 2024). "Inhibitors of mutant IDH1 have been characterized, such as the recently FDA-approved Vorasidenib, a first-in-class dual inhibitor of mutant IDH1 and IDH2 with proven efficacy in IDH-mutant gliomas." (PMID 39518074, 2024). "Mutations in the genes of isocitrate dehydrogenases 1 and 2 (IDH1 and IDH2) play an essential role in the development of a number of tumors (gliomas, chondroid tumors, leukemia), and are important for the diagnosis and choice of therapy." (PMID 38248076, 2024). "In this context, different studies suggested the importance of combined IDH1 and MGMT analysis to predict survival in patients with different types of gliomas." (PMID 38172718, 2024). "In particular, IDH1 and TERT have a significant prognostic impact on gliomas to the extent that they can be used as clear criteria for CNS tumor classification." (PMID 38877400, 2024).
glioma (continued). "Glutamate could support the growth of glioma progenitors irrespective of IDH1 mutation status." (PMID 38673928, 2024). "We also explored the perturbation effects of these genes which suggested that the importance of DPEP1, G6PD, GGT1, GGT5, IDH1, and NFE2L2 for glioma cell survival." (PMID 38819225, 2024). "We further show that this AS signature can be regulated by mutant EGFR or IDH1 and elucidate the functional mechanisms of AS events in genes CERS5 and MPZL1 in promoting glioma malignancy." (PMID 38662454, 2024). "All interactions involving IDH1 and MGMT were included to highlight connections relevant to glioma biology." (PMID 39767713, 2024). "Thirty-one infiltrating glioma FFPE tissue specimens were tested, all of which had known IDH1/2 status as determined by the Oncomine Comprehensive Assay v2 performed as part of routine clinical testing." (PMID 38796421, 2024). "In our study, verbal fluency score (SCOWA test) was an independent predictor of survival in IDH1-wt and MGMT-unmet patients with high-grade gliomas." (PMID 38168519, 2023). "In human gliomas, FBXW7 is downregulated, which inhibits the degradation of SREBP1, which in turn, increases the expression of IDH1." (PMID 37176148, 2023). "While significant differences of normal brain uptake in male and female glioma patients have been described, the effect of normalizing standardized uptake values (SUV) to tumor-to-background ratio (TBR) values in radiomic models predicting IDH1 mutation status is unknown." (PMID 36816966, 2023). "In this study, we cloned the cDNA of IDH1-R132H under the promoter of EF1α and produced a lentivirus to gain the function of IDH1-R132H in CT26 colon cancer cells and GL261 glioma cells." (PMID 37741882, 2023). "IDH1 (and IDH2) were the most predictive for long‐term survival, once again supporting the idea of considering IDHmt grade IV glioma as a distinct category in the 2021 WHO classification of central nervous system (CNS) tumors." (PMID 36776000, 2023). "Based on their prognostic relevance in glioma samples, the seven variables age, FGFR2, IDH1, CDK4, CDK6, KIT, and CDKN2A were selected for the construction of the WHO5 risk signature." (PMID 37273702, 2023). "After ivosidenib treatment, the cachexia syndrome occurred at DPI 17 for the mice bearing wild-type glioma tumor, while at DPI 20 for the mice bearing IDH1 mutant glioma tumor bearing mice." (PMID 37741882, 2023). "Then we analyzed IDH1 gene status and the survival of WHO grade 4 glioma patients received radiotherapy in our center and verified our results by analyzing CGGA and TCGA database." (PMID 37952042, 2023). "A peptide vaccine targeting IDH1R132H (IDH1-vac) was proved safe and effective in stimulating immune response in a multi-center phase 1 trial (NOA-16 trial) in newly diagnosed glioma patients." (PMID 37444531, 2023). "First, we established glioma cell lines that stably expressed IDH1R132H and wild-type IDH1 plasmids." (PMID 37952042, 2023). "Consistently, we found that GSCAR expression was higher in IDH1 wild-type (WT) gliomas than in IDH1 mutant (MUT) gliomas, and glioma patients with higher GSCAR expression exhibited worse clinical outcomes." (PMID 37063420, 2023).
glioma (continued). "IDHmut glioma–induced spikes in spheroids were reduced by both a first-generation IDH1mut inhibitor, AGI5198 (P < 0.0001), and a second-generation IDH1/2 mutant inhibitor, AG881 (P = 0.0008)." (PMID 37104042, 2023). "To address whether IDH1 mutation is involved in antiviral immunity, we first analyzed the publicly available transcriptomic datasets from 3 independent clinical cohorts, including GEO and TCGA, and found that IFN signaling pathways were downregulated in IDH1mut gliomas versus IDH1wt gliomas." (PMID 37880243, 2023). "Age, FGFR2, IDH1, CDK4, CDK6, KIT, and CDKN2A were considered vital indicators related to the prognosis and OS time of glioma." (PMID 37273702, 2023). "Mutations in the NADP+-dependent isocitrate dehydrogenase genes IDH1 and IDH2 are common in acute myeloid leukemia and gliomas." (PMID 36984785, 2023). "IDH (IDH1 and IDH2) genotype and 1p/19q status are important molecular biomarkers in the clinical diagnosis and prognosis evaluation of gliomas." (PMID 37734869, 2023). "We transfected the wild-type IDH1, IDH1R132H plasmids and empty vector into U87MG and U251MG glioma cells and screened them using puromycin." (PMID 37952042, 2023). "TANK was significantly enriched in glioma with WHO grade IV, wild-type IDH1, and GBM (P < 0.05) (P < 0.05)." (PMID 37215097, 2023). "Although a recent clinical trial reported that an inhibitor targeting mutant IDH1 and IDH2 induced durable therapeutic efficacy in lowgrade glioma, the impact of directly targeting mutant IDH for high-grade glioma is under clinical investigation." (PMID 38012788, 2023). "In conclusion, significant prognostic factors for survival in patients with IDH1-wt and MGMT-unmet high-grade gliomas were age and the extent of surgery." (PMID 38168519, 2023). "Two articles used radiomics approaches and machine-learning techniques to predict the molecular markers (IDH1 and MGMT) and prognoses of glioblastomas and gliomas." (PMID 37568660, 2023). "Thus, we believe IDH1 may similarly modulate clinical responses in distinct immunotherapies, tumors, and perhaps even in distinct immune-affected disorders, although we examined DC vaccine therapy for glioma exclusively." (PMID 37161052, 2023). "The results showed that patients in different groups defined by age, FGFR2, IDH1, CDK4, CDK6, KIT, and CDKN2A had significantly different OS in all glioma grades." (PMID 37273702, 2023). "We found that ATRX-d (monoallelic: PR-AUC-E = 0.21, AUROC = 0.71; biallelic: PR-AUC-E = 0.23, AUROC = 0.76) and IDH1-d (monoallelic: PR-AUC-E = 0.24, AUROC = 0.82) in CNS cancers were both predicted by a decreased number of SBS signature 8 mutations." (PMID 36883553, 2023). "IDH1/2 mutant gliomas were re-classified according to the 2021 WHO guidelines into oligodendroglioma (ODG, IDH1/2 mutant and 1p/19q co-deleted) and diffuse astrocytoma (DA, IDH1/2 mutant without 1p/19q co-deletion)." (PMID 35448183, 2022). "In a study of IDH1-mutant (IDH1-mt) gliomas, one study found decreased triglycerides and sphingolipids and elevated pyruvate entering the TCA cycle in IDH1-mt gliomas compared to IDH-wt." (PMID 36643416, 2022). "Proneural glioma are defined by the expression of the neurogenesis markers PDGFRA, NKX2-2, and OLIG2, and they are IDH1 mutants." (PMID 35328529, 2022). "In particular, IDH1 and IDH2 are present in over 80% of low-grade gliomas and a subset of adult glioblastomas." (PMID 35382567, 2022).
glioma (continued). "18F-FGln uptake in gliomas is positively correlated with glioma progression, and can be indicative of gene alterations (PTEN or IDH1) events or response to chemotherapy or radiation therapy." (PMID 36555470, 2022). "Multivariate prognostic analysis showed that age, tumor site, WHO grade, recurrence, Ki-67 expression, IDH1 mutant, ATRX, ASAP3, and NOTCH3 expression were shown to be independent predictive determinants of overall survival in gliomas." (PMID 36382054, 2022). "Here, we demonstrated their correlations with glioma grade, patient survival, and selected genetic patterns in GBMs (WHO grade IV, IDH-1 wild type)." (PMID 36497400, 2022). "Aggressive gliomas, which include GBM, harbor wild-type IDH1 and IDH2 genes (IDHwt), whereas gliomas with better prognosis carry mutated IDH1 and IDH2 genes (IDHmut)." (PMID 35563134, 2022). "The detection of IDH1R132 and IDH2R140/R172 mutations is helpful information to guide the diagnosis of several malignancies such as glioblastomas, gliomas, AITL, MDS, or AML and identify patients eligible for anti‐IDH1 and/or anti‐IDH2 targeted therapies." (PMID 36062346, 2022). "The WHO classification, IDH1 status (Mutant), and MAGED2 protein expression were all found to have a substantial influence on OS and RFS in patients with glioma." (PMID 35892426, 2022). "R132H IDH1 was present in 12% of the GBM samples, suggesting an important role in glioma transformation process." (PMID 35804976, 2022). "In the present study, we used multiple newly implemented techniques to investigate some of the genetic alterations in IDH1, IDH2, CDKN2A, MYB and MYBL1 in pediatric low-grade gliomas." (PMID 35574540, 2022). "Next, we constructed the nomograms with these independent prognosis factors (Age, WHO grade, IDH1 status, 1p/19q status and MD2 expression) to predict 1-, 3- and 5-year survival probability of each glioma patient." (PMID 35372062, 2022). "Furthermore, gliomas with mutated isocitrate dehydrogenase (IDH1 and IDH2) showed elevated levels of oncometabolite D-2-hydroxyglutarate derived from glutamine via glutamate and α-KG conversion, demonstrating the importance of glutamine metabolism in the malignant progression of gliomas." (PMID 35513201, 2022). "Vorasidenib is a potent, oral, brain-penetrant dual inhibitor targeting both IDH1 and IDH2 mutants, which is undergoing a phase III INDIGO study (NCT04164901) in patients with residual or recurrent grade II glioma." (PMID 35814406, 2022). "In IDH1 R132H-negative gliomas, there was a trend toward shorter 5-year PFS (mean = 8.0 months, p = 0.001) and 5-year OS (mean = 28.7 months, p = 0.06) in gliomas demonstrating high EZH2 expression compared with those having low EZH2 expression." (PMID 36292072, 2022). "Our study suggests that TRIM24, IDH1, LBR, HMG20B, USP49 and RCC1 were all highly expressed in glioma tissues and gliomar cell lines both at the mRNA and protein level." (PMID 36246611, 2022). "This discovery was initially made following the finding of gain of function mutations in genes encoding both the cytoplasmic and mitochondrial isoforms of isocitrate dehydrogenase (IDH1 and IDH2, respectively) in high‐grade gliomas and glioblastomas." (PMID 35842901, 2022). "EZH2 was found to be negatively correlated with IDH1 R132H protein expression, in which EZH2 was highly expressed in IDH1 R132H-negative gliomas (p = 0.039)." (PMID 36292072, 2022). "Many of these alterations were consistent with those observed in IDH1-mutant and G-CIMP+ primary gliomas." (PMID 36233525, 2022). "A link between isocitrate dehydrogenase 1 (IDH1) and ZEB1 expression has been reported in lower-grade glioma." (PMID 36402997, 2022).